PAK1 (p21 (RAC1) activated kinase 1)
Diseases named in the same sentence as PAK1 in open-access papers (continued):
Sharing a sentence is not in itself a finding about the gene and the disease.
pancreatitis (1 paper, 2019). Inflammation of the pancreas. "PAK1 knockdown alleviated histological signs of AP such as necrosis of acinar cells and infiltration of inflammatory cells in pancreatitis." (PMID 30718368, 2019). "As PAK1, p38, and NF-κB are activated in cerulein-induced AP mice, and PAK1 inhibition by FRAX597 alleviated pancreatitis symptoms, so we hypothesized that PAK1 played a role in AP through p38 and NF-κB pathway." (PMID 30718368, 2019). "As PAK1 was up-regulated in cerulein-induced AP mice, we hypothesized that PAK1 inhibition might have to function to alleviate pancreatitis symptoms." (PMID 30718368, 2019). "As FRAX597 treatment in cerulein-induced AP mice alleviated pancreatitis symptoms, so the effect of FRAX597 on phosphorylation of PAK1, p38, and p65 in vivo were evaluated." (PMID 30718368, 2019).
prediabetes (1 paper, 2023). "Overall, our new findings reveal that a reduction in PAK1 abundance might promote increased mitochondrial anomalies and increase susceptibility to prediabetes and subsequent progression to T2D." (PMID 37759961, 2023). "Therefore, enhancing skeletal muscle-specific PAK1 signaling could ameliorate muscle metabolic dysfunction, improve insulin sensitivity, reverse prediabetes and prevent progression to T2D." (PMID 37759961, 2023). "We conclude that PAK1 is essential for muscle mitochondrial function, and it is mediated through a p38MAPK/ATF2/PGC1α-axis signaling pathway, providing a new signaling cascade for potential therapeutic interventional strategies to skeletal muscle insulin resistance in prediabetes and T2D." (PMID 37759961, 2023).
premature ovarian failure (1 paper, 2022). "Previous studies showed that miR-23a promotes cell apoptosis in hGCs via the FasL-Fas, ERK1/2, and CDC42/PAK1 signaling pathways, which are related to ovarian reserve function and premature ovarian failure." (PMID 35740072, 2022).
Pseudomonas infection (1 paper, 2023). Infections with bacteria of the genus pseudomonas. "The p21-activated kinase 1(PAK1)/Akt/mTOR pathway is involved in autophagy regulation during Pseudomonas infection in lung epithelium." (PMID 37153108, 2023).
RASopathies (1 paper, 2018). "Our data point to a novel aspect in the molecular pathogenesis of RASopathies as we uncovered RIT1 as regulator of cytoskeletal changes through the RHO GTPases RAC1 and CDC42 and their effector PAK1." (PMID 29734338, 2018).
skin aging (1 paper, 2019). The gradual irreversible changes in structure of skin that occur as a result of the passage of time.. "However, the involvement of PAK1 in UVB-induced skin aging remains unclear." (PMID 31731779, 2019). "Overall, these results indicate that PGG exhibits anti-photoaging effects in vitro and in vivo by the suppression of PAK1 and JNK1 kinase activities, and may be useful for the prevention of skin aging." (PMID 31731779, 2019).
skin squamous cell carcinoma (1 paper, 2020). A carcinoma arising from the squamous cells of the epidermis. "In a KRAS-driven skin squamous cell carcinoma mouse model, deletion of the PAK1 gene led to decreased tumor initiation and progression, thus indicating an important role for PAK1 in Ras signaling." (PMID 32648136, 2020).
small intestinal tumours (1 paper, 2017). "Furthermore reduction of PAK1 mRNA by siRNA treatment decreased the numbers of small intestinal tumours, and the decrease was associated with reduced protein levels of PAK1, active phospho-PAK1 (pPAK1), β-catenin and HIF-1α." (PMID 28629331, 2017).
soft tissue sarcoma (1 paper, 2023). A malignant neoplasm arising from muscle tissue, adipose tissue, blood vessels, fibrous tissue, or other supportive tissues excluding the bones. "Angiogenic switch is a critical process in sustained tumor growth and ensuing metastasis 24 and remains less clarified for its implication in the context of PAK1 overexpression/activation in soft tissue sarcomas." (PMID 37564209, 2023).
sterility (1 paper, 2013). "We have thus identified a spermatogenesis defect caused by loss of max-2 and pak-1, but we do not believe that this defect is the sole source of sterility in these animals." (PMID 23390595, 2013).
subarachnoid hemorrhage (1 paper, 2026). A serious neurological disorder characterized by intracranial hemorrhage into the subarachnoid space. "IPA-3 has been shown to decrease the level of phosphorylated PAK1 in a rat model of subarachnoid hemorrhage and presented anti-angiogenic activity in zebrafish." (PMID 41543887, 2026).
tauopathy (1 paper, 2021). Neurodegenerative disorders involving deposition of abnormal tau protein isoforms (tau proteins) in neurons and glial cells in the brain. "Problem 2 asked participants to predict compounds that bind the Tauopathy pro-targets AURKA, PAK1, FGFR1, and STK11 and avoid the Tauopathy anti-targets PAK3, MAP3K7, and PIK3CA." (PMID 34520464, 2021). "Problem 2 asked participants to predict compounds that bound the Tauopathy pro-targets, AURKA, PAK1, FGFR1, and STK11 and did not bind PAK3, MAP3K7, and PIK3CA." (PMID 34520464, 2021).
tuberculosis (1 paper, 2024). A chronic, recurrent infection caused by the bacterium Mycobacterium tuberculosis. "The bacillus Calmette–Guerin (BCG) vaccine for tuberculosis (TB) has been shown to be effective in the treatment of bladder cancer by macropinocytic delivery, which is dependent on RAC1, CDC42, and its effector PAK1." (PMID 39000072, 2024).
urothelial carcinoma (1 paper, 2020). A malignant neoplasm derived from the transitional epithelium of the urinary tract (urinary bladder, ureter, urethra, or renal pelvis). "Moreover, Rac1 activity and increased levels of PAK1 expression were associated with lymph nodes metastasis in urothelial carcinoma." (PMID 32351958, 2020).
ZIKV infection (1 paper, 2021). "Further investigation identified the GTPase domain of RhoV to be critical for its proviral phenotype, while siRNA-mediated knockdown of RhoB, another Rho GTPase, and Pak1, the direct effector of RhoV, leads to reduced ZIKV infection." (PMID 34834920, 2021). "Therefore, we investigated whether other Rho GTPases and effector protein of RhoV, Pak1, carry similar functions as RhoV during ZIKV infection in SNB-19 cells." (PMID 34834920, 2021). "Therefore, we asked whether other related Rho GTPases and RhoV effector proteins such as Pak1 are also able to enhance ZIKV infection." (PMID 34834920, 2021).
cancer (256 papers, 2008 to 2026). A tumor composed of atypical neoplastic, often pleomorphic cells that invade other tissues. "More broadly, PAK1 has been implicated in cancer, neurofibromatosis, diabetes, and hypertension, highlighting its targeting as having broad therapeutic potential." (PMID 41451871, 2025). "In various cancers, PAK1 activation is closely linked to resistance mechanisms against standard therapies." (PMID 40001545, 2025). "Aberrant PAK1 activity has been implicated in the progression of several human diseases, including cancer, heart disease, and neurological disorders." (PMID 40001545, 2025). "On the other hand, since increased Pak1 activity is associated with cancer progression, there has been a significant effort to develop Pak1 inhibitors." (PMID 40065530, 2025). "We previously showed that PAK1 modulates macropinocytosis of Matrigel, collagen I, normal fibroblast- and cancer-associated fibroblast-CDM." (PMID 39666682, 2024). "Amplification of PAK1 and high PAK1 protein levels are found in several human cancers, including BC, and are linked to aggressive tumour types, chemotherapy resistance and poor prognosis." (PMID 37368917, 2023). "Increased PAK1 activity and expression have been linked to several human malignancies, primarily cancer." (PMID 37190165, 2023). "One such factor, implicated in cancer responses to multiple treatment modalities, is p21RAC1-activated kinase 1 (PAK1)." (PMID 37830586, 2023). "Taken together, these data cast important new insights into the nature of PAK1 dysregulation in cancer, including its possible causes and potential consequences." (PMID 36064705, 2022). "As such, activated RAC1 relays transforming information downstream of over-expressed FAK or mutated KRAS in cancer cells, mainly by binding to and activating its effectors PAK1-3." (PMID 34638434, 2021). "A biomarker‐guided targeted therapeutic approach for metastatic OS and other cancers harboring p27 mislocalization can be developed, where cytoplasmic p27 is used for risk stratification and PAK1 can be exploited as a potential therapeutic target." (PMID 31872963, 2020). "The overexpression of P21-activated kinase 1 (PAK1) is associated with poor prognosis in several cancers, which has emerged as a promising drug targets." (PMID 32752894, 2020). "The association of down-regulation of PAK1 with decrement of PD-L1 induced by CBD alone and CBD plus THC suggested that these cannabinoids inhibited the expression of PD-L1 by cancer-associated PSC cells through a PAK1-mediated pathway." (PMID 33126623, 2020). "In previous results, we revealed that activation of PAK1 in Smad4 deficient cancers suppresses PUMA-mediated apoptosis." (PMID 28423593, 2017). "Since PAK1 inhibitors has been suggested as putative candidate for NF2 deficient cancers including NF2 syndrome, IPP-14 would be one of plausible chemicals for NF2 syndrome and other cancers." (PMID 28423593, 2017). "Among the PAKs family, PAK1 is the most extensively studied member in group I PAKs; its oncogenic role and the underlying mechanisms have been investigated in a wide variety of cancers." (PMID 25093037, 2014). "Increased activity of Rac1 and overexpression of Pak1 are associated with the progression of cancer, but most of the evidence has come from cell culture studies." (PMID 20426825, 2010). "Given that structural variants in other kinases have been shown to promote cancer, future research should explore whether PAK1 variants have similar oncogenic potential." (PMID 39756822, 2025). "In addition to cancer progression, PAK1 functions have been implicated in aging, neurodevelopmental disorders, liver disease, immune system abnormalities, and cardioprotection." (PMID 40001545, 2025). "PAK1 is susceptible to inhibition by a number of ATP-competitive and allosteric inhibitors that have been developed to counteract its dysregulated activity in diseases such as cancer." (PMID 40001545, 2025).
cancer (continued). "Dysregulation of PAK1 is associated with drug resistance in several cancers." (PMID 37537668, 2023). "PAK1, downstream of Rac1 and cdc42 in the Rho family, induces actin polymerization to regulate basic cell migration and is associated with healthy cells as well as with cancer growth, migration, and invasion." (PMID 38188678, 2023). "Although they exert cardioprotective effects, the association of Pak1/2 with cancer could limit their cardiovascular applications." (PMID 39899001, 2022). "Indeed, the PAK1-induced mechanism of CRC resistance to 5-FU is partly associated to the expression of cancer stem cell markers and the CD44 subtype profile." (PMID 36230657, 2022). "In contrast, in pathological conditions, deletion of Pak1 is sufficient to amplify cardiac muscle hypertrophy in response to pressure overload, while Pak1 overexpression mitigates muscle atrophy caused by cancer cachexia." (PMID 34220542, 2021). "Treatment of endometrial cancer (Ishikawa cells) with Uro-A (20 μM) significantly decreased the activity and mRNA levels of Rac1 and PAK1, and this resulted in actin depolymerization, which is associated with a decreased cancer cell proliferation and migration." (PMID 34164422, 2021). "PAK1 dysregulation has been documented to be closely associated with cancer cell proliferation, metastasis, and drug resistance, and it has emerged as a promising target for cancer treatment." (PMID 32863957, 2020). "Thus, specific binding inhibitor of PAK1-PUMA would induce cell death in Smad4-deficient or PAK1 activated cancers." (PMID 28423593, 2017). "Thus, selective PAK1 inhibitor has been proposed to be potent candidate target for NF2 syndrome as well as NF2 deficient human cancers such as mesothelioma." (PMID 28423593, 2017). "Therefore, we propose that by repressing Pak1 expression, Rb prevents Rac1 hyperactivity usually associated with cancer and related to cytoskeletal derangements that disrupt cell adhesion, consequently enhancing cancer cell migratory capacity." (PMID 26555075, 2015). "There has been mounting evidence that PAK1 is tightly related to the progression of cancer and may become a promising diagnostic and therapeutic target for cancer." (PMID 25888627, 2015). "PAK1 in particular has been associated with a variety of pathological conditions, including cancer." (PMID 22869096, 2012). "Furthermore, PAK1 has come to be seen as a cancer hallmark which regulates cytoskeleton dynamics, proliferation, metabolism reprogramming, mitosis, invasion, metastasis, tumor microenvironment response, cancer cell immune escape and cancer drug resistance." (PMID 32863957, 2020). "Thus inhibition of PAK1 should reverse the suppression and/or deficiency in the immune system, and hence up-regulate the immune system to promote a stronger immune response in disease settings such as cancer." (PMID 28629331, 2017). "Mechanistically, loss of PAK1 promoted mRNA decay and inhibited the expression of CD44, SAA1, MTOR, RPS6KB1, and EIF4G1, the factors involved in tumorigenesis in many cancers." (PMID 41459112, 2026). "A previous study showed that PAK1 kinase is stimulated by PDGFRa upon growth factor binding in cancer cells." (PMID 40586933, 2025). "In view of the evidence that Pak1 promotes tumorigenesis, there is an extensive literature on the potential of inhibition of Pak1 in cancer therapy." (PMID 40065530, 2025). "Due to its role in promoting cell survival and proliferation, PAK1 kinase is frequently overexpressed in cancer cells." (PMID 41516310, 2025). "PAK1 is an important cancer-promoting protein that regulates several important cancer proliferation and metastasis pathways, and strongly contributes to metabolic reprogramming and malignant metastasis of cancer." (PMID 40302782, 2025). "The action of UA leads to a reduction in Rac1 activity and PAK1 phosphorylation, which contributes to the inhibition of cancer." (PMID 40867609, 2025).
cancer (continued). "Yin and colleagues stratified BC patients into high and low risk cancers based on a seven gene expression assay (BATF, CD3D, HLA-DQB2, JUN, MAP2K6, NFKBIE, PAK1)." (PMID 40148963, 2025). "Within the MAPK/RAS signaling pathway, B-raf_pS445, MNK1, and PAK1 were found to be increased in cancer following RPPA analysis." (PMID 41284888, 2025). "As with the development of cancer‐related therapies, blocking the effects of Pak1, activation of Pak1 requires an emphasis on tissue‐specific targeting." (PMID 40065530, 2025). "We aimed to establish the regulatory link of Pak1 and pyruvate metabolism—a pathway of prime importance, which lies in the distinction between normal and cancer cells." (PMID 40090587, 2025). "In cancer, PAK1 is involved in facilitating immune evasion13and does so by modulating immune surveillance." (PMID 40783411, 2025). "In turn, there is a need for the determination of the broad effects of inhibition of Pak1 kinase activity on cardiac function, adipose, and pancreatic function in humans and animal models with cancer." (PMID 40065530, 2025). "For instance, in non-small cell lung cancer (NSCLC), PAK1 enhances β-catenin-mediated cancer stemness, stabilizing markers such as OCT4 and SOX2 and driving tumor aggressiveness and chemoresistance." (PMID 40001545, 2025). "Recent advances highlight the therapeutic potential of targeting PAK1 as a strategy to address cancer progression and therapy resistance." (PMID 40001545, 2025). "In PDA, PAK1 has been shown to inhibit cancer cell apoptosis and suppress intra-tumoral infiltration of CD4+ and CD8+ T-cells." (PMID 40943273, 2025). "Targeting PAK1-regulated Wnt/β-catenin signaling has shown potential to improve drug sensitivity across multiple cancers." (PMID 40001545, 2025). "The pro-tumorigenic properties of PAK1, along with its high expression in tumor cells, have established this protein as a persistent therapeutic target in cancer treatment." (PMID 41516310, 2025). "Our comprehensive analysis of PAK isoform dependencies, alterations, and their impact on patient survival across a range of cancers highlights the significant and context‐specific roles of PAK1 and PAK2, along with other PAK family members." (PMID 39756822, 2025). "Consistently, PAK1KD CM reduced the tube-forming capacity of endothelial cells, further highlighting the role of PAK1 in promoting angiogenesis through cancer-cell-derived paracrine signalling." (PMID 41294859, 2025). "Below, we highlight the accessory proteins involved in PAK1 modulation and their roles in various types of cancers and developmental disorders, opening new avenues for therapeutic intervention, with these candidates emerging as promising targets." (PMID 40001545, 2025). "The reduced vessel density observed in PAK1KO tumours likely reflects impaired paracrine signalling from cancer cells that normally activate PAK1-dependent endothelial pathways." (PMID 40943273, 2025). "In the 20 years since it was found to be effective in the proliferation and progression of breast cancer, the role of PAK1 in cancer formation continues to be investigated." (PMID 40864802, 2025). "PAK1 is implicated in cytoskeletal remodelling and endothelial permeability, whereas PAK4 influences cancer cell survival, stemness, and therapy resistance." (PMID 41228228, 2025). "To explore the molecular changes involved, we conducted an unbiased proteomic study to compare the protein profiles of PAK1KO, PAK4KO, and PAK1&4KO cancer cells with WT cancer cells." (PMID 41228228, 2025). "This is confirmed in inhibition of Pak1 in cancer pathologies in which there is an interplay between Hippo signaling and Pak1 activity." (PMID 40065530, 2025). "Mutations in upstream GTPases, such as RAC1, RAC2, and RAS, can lead to the hyperactivation of PAK1, linking oncogenic signaling to phenotypic changes in cancer cells." (PMID 40001545, 2025).